LEP (leptin)
Diseases named in the same sentence as LEP in open-access papers (continued):
Sharing a sentence is not in itself a finding about the gene and the disease.
sleep disorder (24 papers, 2014 to 2026). A change from the patient's baseline sleeping pattern, in the hours slept and/or an alteration/dysfunction in the stages of sleep. "Sleep disorders are also related to brain-gut peptidessuch as melatonin, somatotropin and leptin, which can lead to functionaldyspepsia and increase the risk of sleep disorders." (PMID 40071357, 2025). "Leptin is by far the most intensely studied adipokine concerning sleep physiology and sleep disorders." (PMID 35163627, 2022). "In summary, leptin has been shown to have significant roles in sleep physiology and sleep disorders." (PMID 35163627, 2022). "There is a particular interest in looking at the roles of leptin in sleep disorders among different patient populations with metabolic dysfunction." (PMID 35163627, 2022). "Recent literature indicates that some adipokines, such as leptin, have direct roles in sleep physiology and sleep disorders." (PMID 35163627, 2022). "The aim of this study was to assess the nocturnal profile of total ghrelin, obestatin, and leptin in patients with elevated BMI and to investigate the impact of breathing-related sleep disorders on these hormone levels." (PMID 35407646, 2022). "Sleep disorders are believed to result in an increase in the body mass index because of reduced leptin levels, elevated thyroid-stimulating hormone levels, increased glucose tolerance, and increased ghrelin levels." (PMID 33922616, 2021). "Insufficient sleep is related to inducing changes in the leptin and ghrelin hormones and can induce changes in the metabolism, thereby contributing to sleep disorders as well as an increase in the BMI." (PMID 33651799, 2021). "In addition, the nocturnal secretion of the appetite-related hormone leptin is reduced due to sleep disorders, which leads to an increase in total energy intake to energy imbalance." (PMID 36245534, 2022). "Due to alterations in leptin concentrations following sleep fragmentation (SF) in obstructive sleep apnea (OSA), it has been hypothesized that leptin can be used as a biomarker to detect the presence of sleep disorders." (PMID 29479505, 2018). "In addition, sleep disorders can result in appetite-regulating hormone imbalance (e.g., in leptin and ghrelin)." (PMID 27980794, 2016). "Therefore, the aim of this observational study was to assess the nocturnal profile of total ghrelin, obestatin, and leptin in patients with elevated BMI and investigate the impact of breathing-related sleep disorders on the levels of appetite-regulating hormones." (PMID 35407646, 2022). "Thus, orexin-A and leptin may be important factors in sleep disorders." (PMID 24864160, 2014). "Leptin, AMP activated protein kinase (AMPK), and fatty acid oxidation were found to have global influence in the network and represent potentially important interventional targets for metabolic and sleep disorders." (PMID 35892989, 2022). "On the other hand, sleep disorder may adversely affect GERD by increasing intraesophageal stimulation (e.g., gastric acid) and increasing esophageal exposure to gastric acid, possibly by changing the ghrelin and leptin ratio." (PMID 33917336, 2021).
viral infection (24 papers, 2005 to 2024). "Our findings raise the possibility that leptin signaling is implicated in preserving autonomic function after severe viral infection." (PMID 39480494, 2024). "Using functional experiments in mouse models of viral infection, we demonstrate that increased leptin is causally related to impairment of antiviral immunity in macrophages." (PMID 37857661, 2023). "Noteworthy, leptin has been proved to be a key player in IR of liver cirrhosis independently of the disease etiology (alcohol consumption or virus infection), and IR is associated with a worse prognosis." (PMID 33316927, 2020). "Hyperleptinemia and leptin resistance are characteristics of the obese, and there is strong evidence that inefficient leptin signalling contributes to the higher susceptibility for bacterial and viral infections and the impaired immune response of obese patients." (PMID 37238973, 2023). "According to this, we speculate that the excess weight of mothers causes an increase of leptin in children under 6 months who receive breastfeeding, and this could have an impact on the severity of viral infections." (PMID 32133330, 2020). "Or that anorexia nervosa develops, in some patients, when variant viral proteins with aberrant leptin-agonist function arise during the course of viral infection, as the temporal relationship between infection and disease onset, very clearly documented in one study, suggests." (PMID 16115320, 2005). "This association between leptin resistance and the severity of a viral infection may be attributed to leptin’s supportive role in the maturation, development, and function of B cells, as well as its roles in modulating lymphocytes and inhibiting the CD8+ T cell response." (PMID 39457167, 2024). "In contrast, leptin resistance may increase the susceptibility to virus infection." (PMID 33316927, 2020). "Instead, leptin treatment prevented profound bradycardia and hypothermia that was seen after viral infection in ob-ctrl mice." (PMID 39480494, 2024). "There are very few human studies on the interrelated effects of leptin signaling in infectious diseases, especially in severe viral infections, and there is a need for better understanding of circulating leptin." (PMID 35052684, 2021). "Very little is known about plasma levels of leptin during severe viral infections demanding treatment in the ICU." (PMID 35052684, 2021). "There is some data reported in literature on the effects of hyperleptinemia, which leads to leptin resistance, on the immune response to viral infections." (PMID 33907162, 2021). "Compared to Ts virus infection, V virus resulted in higher glucocorticoids (GCs) and lower leptin level in plasma." (PMID 23251416, 2012). "Very little is known about leptin in severe viral disorders." (PMID 35052684, 2021). "Viral infections cause the elevated SOCS3 expression, which inhibits leptin signaling." (PMID 29868503, 2018). "Leptin resistance has been demonstrated in immune cells such as NK cells, T cells, and monocytes, and this might contribute to suboptimal immune responses to viral infection in obese individuals." (PMID 33804765, 2021). "Therefore, an upregulation of SOCS3 during viral infections may, both directly and by decreasing leptin expression, dampen innate and adaptive immunity." (PMID 33804765, 2021). "Several studies on mouse models of viral infection addressed the role of LEPR and leptin in the pathogenesis of infectious diseases." (PMID 36589459, 2022). "Furthermore, cytokine profiles in chronic hepatitis B non-HCC patients differed from those of patients with non-viral disease with AUROC = 0.840 with leptin, resistin, IL-8, M-CSF, TNF-β, and sFas ligand as the top 6 cytokines with distinguishing levels." (PMID 28928388, 2017).
viral infection (continued). "Other strongly enriched protein classes were related to viral infection [Hepatitis B (q < 10-28), Epstein–Barr (q < 10-21), HIV (q < 10-17), and Herpes simplex (q < 10-15)] and signaling pathways [TNFalpha (q < 10-28), TGFbeta (q < 10-24), and Leptin signaling (q < 10-23)]." (PMID 26300911, 2015). "Lower leptin level even absent was observed in V infection group, and it may be expected to contribute to the effect in virus infection." (PMID 23251416, 2012). "Nevertheless, analyzing this dataset suggested that leptin and LEPR are neither important for immune response nor to the degree of sensitivity of chicken spleens to viral infection." (PMID 31514326, 2019).
glioma (23 papers, 2009 to 2025). A benign or malignant brain and spinal cord tumor that arises from glial cells (astrocytes, oligodendrocytes, ependymal cells). "We substantiated the idea of TERT and LEP being the risk factors, and LEP and PON1 as protective factors, affecting the immune cell infiltration level and the levels of proinflammatory factors in glioma." (PMID 34114970, 2021). "Consensus clustering analysis was used to sort glioma samples into two clusters according to the expression profile of four survival-associated AGs (TERT, LEP, PON1, and SSTR3)." (PMID 34114970, 2021). "A prognostic risk model was constructed according to four selected AGs (LEP, TERT, PON1, and SSTR3) in the TCGA dataset and Chinese Glioma Genome Atlas (CGGA) database." (PMID 34114970, 2021). "Leptin released from glioma cells partially contributes to angiogenesis, as evaluated by induced tube formation capacity in human umbilical vein endothelial cells (HUVECs) via STAT3 phosphorylation." (PMID 33316976, 2020). "It has also been demonstrated that leptin enhances the invasive potential of glioma stem-like cells, and high expression of ObR leads to temozolomide resistance through increased stem/progenitor cell features." (PMID 32526957, 2020). "First, the present study analysed intracellular signalling via CCK and leptin in rat C6 glioma cells." (PMID 32686770, 2020). "Grade III gliomas showed moderate leptin expression in most of the cases (80%) while strong expression was noted in only two cases." (PMID 30803210, 2019). "Further, the interactions between leptin and other signaling pathways, such RTK signaling, that have been implicated in gliomas are yet to be analyzed." (PMID 30803210, 2019). "Leptin is one of the cytokines produced by the adipose tissue that is known to be involved in glioma tumorigenesis." (PMID 30803210, 2019). "Our findings are also consistent with previous finding where leptin induces nitric oxide synthase type II in C6 glioma cells via NFκB." (PMID 23383125, 2013). "Barbara Morash and colleagues provided the first report of leptin expression in glioma following detection of leptin expression in the rat C6 glioma cell line." (PMID 22263109, 2012). "This suggests that leptin/ObR autocrine/paracrine signaling increases the malignant characteristics of gliomas." (PMID 22263109, 2012). "Within gliomas, there is a correlation between tumor grade and tumor expression of leptin and its receptor." (PMID 22263109, 2012). "Other reports demonstrated that rat glioma tissues and cell lines express leptin mRNA, and that in rat C6 cells leptin can increase survival and enhance migration and invasion of these cells." (PMID 21771332, 2011). "For instance, a positive correlation between leptin levels and glioma was found." (PMID 37509120, 2023). "Recently, a positive correlation between circulating levels of leptin and glioma has been found." (PMID 37509120, 2023). "The angiotensin and LEP played a regulatory role in glioma cells." (PMID 36193059, 2022). "In view of the dynamic and highly complex nature of the relation between leptin/ObR and glioma biology, combined multi-stage diagnostics have been recommended in order to appropriately distinguish, interpret and most importantly enhance the sensitivity/specificity ratio of serum sample analytics." (PMID 33316976, 2020). "Interestingly, transformation of low-grade gliomas into the more aggressive and lethal glioblastoma multiform (GBM) is associated with overexpression of intra-tumoral leptin as well as increased angiogenesis." (PMID 33316976, 2020). "In rat C6 glioma cells, leptin pre-treatment enhanced Ca2+ mobilization by a CCK agonist (CCK-8s)." (PMID 32686770, 2020). "Leptin has been recognized as a potential tumor growth promoter in various cancers including cranial tumor pathologies such as pituitary adenomas, meningiomas and gliomas." (PMID 33316976, 2020). "Unfortunately, most of what is known about leptin and glioma stems from the rat C6 cell line." (PMID 22263109, 2012).
glioma (continued). "Furthermore, the expression of the leptin-ObR system correlates with histological grade: GBM has the greatest levels of leptin and ObR while low-grade gliomas have the least." (PMID 22263109, 2012). "Other studies demonstrated leptin mRNA expression in rat glioma tissues and cell lines." (PMID 21771332, 2011). "However, the potential role of intratumoral leptin in glioma progression, especially in the regulation of angiogenesis, has never been addressed." (PMID 21771332, 2011). "Leptin and related mediators of immune-metabolic traffic have attracted increased recognition in the past decade in brain tumor biology, in particular potential implications in the diagnosis and treatment of recurrent and newly diagnosed high and low grade gliomas." (PMID 33316976, 2020). "Inhibition of leptin action using specific antagonists and inhibitors against specific signaling pathways might prove promising for the treatment of gliomas and effective management in these patients with glioma to increase their quality of life." (PMID 30803210, 2019). "The current study provides initial insights toward the understanding of the probable involvement of leptin and its receptor in diffuse glioma tumorigenesis, indicating that the leptin system may be involved in glioma pathogenesis through autocrine or paracrine mechanisms." (PMID 30803210, 2019). "Although leptin and ObR involved in angiogenesis in glioma has been reported on previous study, the relationship between ObR expression and VM formation in human glioblastoma tissues and the relevance of their co-existence within glioblastoma invasion or prognostic significance remain unclear." (PMID 28938545, 2017). "However, hypoxia, which is a characteristic of solid tumors, is more pronounced with higher grades of glioma and may explain the increased expression of leptin and ObR in GBM compared to lower-grade glioma." (PMID 22263109, 2012). "Leptin has been shown to induce or to potentiate together with interferon γ (IFNγ), with tumor necrosis factor α (TNFα) or with IFNγ and IL-1β, NO production in murine J774A.1 macrophages, rat adipocytes, C6 glioma cell-line, and rat vascular smooth muscle cells (VSMCs)." (PMID 19688109, 2009). "The four selected AGs (LEP, TERT, PON1, and SSTR3) were concluded to have important functions in immune cell infiltration of glioma." (PMID 34114970, 2021). "Furthermore, leptin was observed to stimulate tube formation and enhance proliferation of endothelial cells directly, and the peptide ObR antagonist could inhibit these pro-angiogenic effects of leptin derived from glioma cells." (PMID 28938545, 2017). "Furthermore, it has been demonstrated that LDFI, a peptide able to block ObR, along with AG490, a JAK2/STAT3 inhibitor, is able to reduce leptin-induced NOTCH1 overexpression and transcriptional activity in U87 and T98 glioma cell lines." (PMID 37509120, 2023). "Interestingly, VEGF also activated angiogenesis through STAT3 phosphorylation, and co-inhibition of the receptors for both leptin and VEGF suppressed angiogenesis in HUVECs induced by conditioned medium from glioma cells more than either antagonist alone." (PMID 33316976, 2020). "Previously, leptin was reported to be able to increase the expression of MMP-2, MMP-7 or MMP-9 in different cancer cells, as well as the expression of MMP-13 in glioma cells." (PMID 25948792, 2015). "The ability of leptin to induce iNOS gene expression has been shown in several cell types, such as murine J774A.1 macrophages, rat adipocytes, human primary chondrocytes and ATDC5 cells, C6 glioma cell line, and human OA cartilage." (PMID 20592755, 2010). "Similarly, leptin enhances the production of matrix metalloproteinase (MMP)-13 through the p38-mitogen activated protein (MAP) kinase and nuclear factor (NF)-κB pathway, thus promoting the migration and invasion of C6 glioma cells." (PMID 36105407, 2022).
glioma (continued). "Our results revealed the expression of PON1 was crucially positive associated with SSTR3 in glioma, while there were a crucial negative association between the expression of PON1 and TERT, and the expression of LEP was negatively associated with PON1 and SSTR3." (PMID 34114970, 2021). "Furthermore, glioma cells expressed high levels of leptin and leptin receptors than nonmalignant astrocytes and increase proliferation, migration and secretion of several MMPs, MMP2, 9 and 13 by leptin activation of p38 MAP kinase and NFκB pathways." (PMID 24202338, 2013).